MIR675 (microRNA 675)
Synonyms: hsa-mir-675; MIRN675
Gene: MicroRNA gene on chromosome 11 (1,996,759 to 1,996,831, reverse strand). Ensembl gene ENSG00000284010.
Gene Ontology:
Biological process: miRNA-mediated post-transcriptional gene silencing
Cellular component: RISC complex
Homologues: Orthologues: chimpanzee MIR675 (100% identical), macaque mml-mir-675 (99% identical), guinea pig MIR675 (93% identical), mouse Mir675 (92% identical).
Diseases named in the same sentence as MIR675 in open-access papers:
MIR675 is named in the same sentence as 2 diseases in open-access papers, as found by Europe PMC text mining. Sharing a sentence is not in itself a finding about the gene and the disease. The quoted sentences say what the papers report.
breast carcinoma (1 paper, 2015). "It would be interesting to investigate if H19 and MIR675 regulate the expression of the GATA3 gene, which is known to play a role in breast cancer development as well as the development and maturation of luminal cells in the mammary gland." (PMID 25944846, 2015).
tumor (1 paper, 2015). "The xenograft tumor showed that tumor tissue possessed more poor-differentiation cells in mature mir675 overexpression group than that of control group, and less poor-differentiation cells in mir675 knockdown group than that of control group." (PMID 26376677, 2015).